IL10 (interleukin 10)
Diseases named in the same sentence as IL10 in open-access papers (continued):
Sharing a sentence is not in itself a finding about the gene and the disease.
Sepsis (continued). "In a sepsis model using lipopolysaccharide (LPS), injection of the N-glycan upregulated serum IL-10, and suppressed pro-inflammatory IL-1β, TNF-α and IFN-γ." (PMID 33727664, 2021). "Partial depletion of Tregs elevated IL-17A, IL-1β, and IL-6 production and decreased IL-10 levels, leading to lower bacterial load and attenuation of lung injury in secondary P. aeruginosa infection after sepsis." (PMID 34222495, 2021). "AE prominently downregulated CXCL-1, CXCL-8, IL-6, TNF-α, Glu1, and HMGB1 mRNA expression but activated IL-1RN, IL-10, Sirt-1, and Nrf-2 mRNA expression in the lung during sepsis." (PMID 34493741, 2021). "The levels of the proinflammatory cytokines TNF-α, IL-1β, IL-6, IL-12p70, and IL-10 in the serum and in the lungs of the A. baumannii-derived sepsis mouse model treated with IOX1 were significantly reduced." (PMID 33536477, 2021). "The expression of anti-inflammatory cytokines including IL-10 is predominately occurring during the second phase of neonatal sepsis which reflects the upregulation of immunosuppressive mechanisms." (PMID 34676267, 2021). "Studies of experimental sepsis have indicated that HBO2 treatment exerts its antimicrobial effect by enhancement of IL‐10, which lowers IL‐6 and thereby reduces the overall mortality in HBO2‐treated animals." (PMID 33719215, 2021). "In a human study, the IL-10/lymphocyte ratio was significantly higher in non-surviving patients than in surviving patients, indicating sepsis-induced IL-10-related immunosuppression." (PMID 34371879, 2021). "Several reports have demonstrated that TNF-α, IL-6, and IL-10 can serve as both makers and mediators of sepsis severity and that elevated cytokine levels predict mortality following CLP." (PMID 35003518, 2021). "Secondary elevation of IL-10 can be a poor prognosis of common bacterial infection, sepsis, and MOF in trauma patients." (PMID 35126355, 2021). "Compared with those in the CLP + DEX group, the levels of TNF-α, IL-1β, and IL-10 increased significantly in the CLP group at 6 h after sepsis induction." (PMID 33981237, 2021). "IL-10 drives the molecular pathway that enhances immunosuppression during late sepsis, which correlates with mortality in patients with infection." (PMID 35069560, 2021). "IL-10 agonism has also been demonstrated to reduce white matter damage in neonatal rats following maternal sepsis, suggesting a neuroprotective effect." (PMID 34712631, 2021). "As expected, N-glycans isolated from C. stellatoidea (Candida albicans (Robin) Berkhout) and C. parapsilosis (non-albicans strain) significantly induced large amounts of IL-10 in comparison with J-1012 N-glycan in the sepsis model." (PMID 33727664, 2021). "In the present study, IL-1b and IL-10 levels had significant predictive value only in the group of patients with sepsis." (PMID 33917002, 2021). "Activation of A2AR by endogenous adenosine contributed to the production of interleukin-10 (IL-10) in polymicrobial sepsis." (PMID 33567540, 2021). "Whereas sepsis patients exhibiting low bacterial load predominantly release the cytokine, interferon-gamma (IFNγ), the inflammation-inhibiting cytokine, interleukin-10 (IL-10), prevails in bacteremic patients with a high bacterial load." (PMID 34964952, 2021). "Elevation of serum IL-6 and IL-10 levels has been reported in the initial phase of the immune response to sepsis." (PMID 34793546, 2021). "IL-10 functions as a temporal regulator of the transition from early reversible sepsis to the late phase of irreversible shock." (PMID 34371879, 2021). "While levels of IL-6 and IL-10 strongly increased in control patients, patients with postoperative sepsis were unresponsive to LPS stimulation, hinting towards sepsis-induced cellular anergy at the time of study inclusion." (PMID 33939725, 2021).
Sepsis (continued). "Our approach, based on a putative immune suppressing mechanism of C. albicans, points to its potential to control IL-10 production leading to amelioration of both the early hyper- and late hypo-immunoreactivity in sepsis." (PMID 33727664, 2021). "Plasma levels of the anti-inflammatory cytokine IL-10 increased also progressively with the severity of sepsis, reaching similar levels in clopidogrel- and vehicle-treated mice." (PMID 34447900, 2021). "Previous research reported that higher plasma IL-10 concentrations contributed to higher mortality of sepsis." (PMID 35003518, 2021). "In our study, only SeSP rats reveal an increase of plasmatic IL‐10 level 2 h after sepsis induction." (PMID 34288548, 2021). "In our study, the animals with sepsis developed proinflammatory profiles that were characterized by increased expression of IL-1β, IL-10, IL-6 and TNF-α." (PMID 33676566, 2021). "Increased survival was also reported in a murine sepsis model following indirect reduction of Tregs through IL-10 and TGF-β neutralization." (PMID 33021569, 2021). "In both cellular and murine systemic models of sepsis, the treatment with modified nanocarriers alleviated inflammation through increased expression of interleukin-10 (IL-10) in macrophages." (PMID 34299113, 2021). "Increased blood levels of IL-6 and IL-10 have been clinically related to the high rate of mortality in patients with severe sepsis." (PMID 32117251, 2020). "Significant differences were observed in the expression of the pro-inflammatory cytokine genes IL-2, IL-6, TNF, and IFN-γ and the anti-inflammatory cytokine genes IL-4 and IL-10 between sepsis patients and healthy controls." (PMID 32922168, 2020). "Melatonin decreases stress-induced inflammation and reduces the inflammatory response in the case of sepsis due to a decrease in the level of interleukin-10 (IL-10)." (PMID 33456605, 2020). "Silencing circDNMT3B can significantly increase the level of d‐lactic acid, FD‐40, MDA, diamine oxidase, IL‐10 and IL‐6, compared with sepsis group, while the SOD activity was lower." (PMID 32383354, 2020). "Patients with sepsis typically have elevated blood levels of endotoxins and cytokines [e.g., interleukin 6 (IL-6), IL-8, IL-10, and tumor necrosis factor alpha(TNF-α)]." (PMID 32144519, 2020). "It has been shown that higher IL-6 and TNF-α levels are associated with a higher risk of developing sepsis, and that, among patients with sepsis, men had worse outcomes, higher TNFα, and lower IL-10 levels than women." (PMID 32485823, 2020). "A number of anti-inflammatory cytokines are upregulated during the course of sepsis (e.g., IL-1RA, IL-4, IL-10, and TGF-β)." (PMID 32676795, 2020). "Endogenous IL-10 is an important anti-inflammatory cytokine, prevents animals from death in sepsis and has been recognized as a key approach for dealing several inflammatory disorders." (PMID 33158114, 2020). "The detection of inflammatory mediators of each group showed that LPS significantly increased the levels of TNF-α, IL-6, IL-1β, and MCP-1, and decreased the level of IL-10, consistent with those results discovered in mice with sepsis-induced kidney injury." (PMID 33197894, 2020). "Serum cytokines, including IL-6, IFN-γ, TNF-α, and IL-10, were elevated in the control groups and in SnPP-treated rats indicating sepsis." (PMID 32015027, 2020). "P2X7R pharmacological blockade with BBG decreased levels of inflammatory cytokines (i.e., IL-1β, IL-6, and IL-10), NO production, and neutrophil recruitment to the peritoneal cavity in a mouse model of sepsis." (PMID 33519492, 2020). "Lower levels of IL-18 found in both sepsis groups can be explained by the overexpression of IL-10, because there is an inverse regulatory function between IL-10 and IL-18." (PMID 32295272, 2020). "Regulatory T cell-derived exosomes increased IL-10 and decreased IL-6 production of dendritic cells upon LPS stimulation, indicating their contribution to immunosuppression in sepsis." (PMID 33013905, 2020).
Sepsis (continued). "The injection (i.v.)of hUCB-MSCs alleviated the severity of LPS-induced sepsis by increasing IL-10 levels (p < 0.001) and decreasing mortality (p < 0.05) in septic mice." (PMID 32014040, 2020). "The number of DCs is indeed reduced in patients with sepsis; however, the differentiation of monocytes into DCs is accelerated, and it has been demonstrated that IL-10–treated DCs are able to suppress the activation of T cells and cause T cell anergy." (PMID 33336293, 2020). "Other cytokines, such as IL-1β, IL-6, and IL-10, can be used for the diagnosis of sepsis and evaluating the inflammatory responses and the prognosis for ARDS patients." (PMID 32566670, 2020). "By contrast, previous studies have demonstrated that the MSCs significantly reduced systemic cytokines and chemokines (IL-6, IL-1b, IL-10, KC, and CCL5) after 28 h of administration in the sepsis-associated inflammation mouse model." (PMID 32903481, 2020). "Consistent with sepsis pathology, anti-inflammatory cytokines, IL-4 and IL-10, contained in exosomes of sepsis mice increased in the late phase." (PMID 33013905, 2020). "The increased production of IL-10 by some specific cell subpopulations has only partially been described in sepsis." (PMID 33613540, 2020). "Biomarkers of sepsis so far evaluated in horses include interleukin-1β (IL-1β), interleukin-10 (IL-10), interleukin-6 (IL-6), serum amyloid A (SAA), soluble CD14 (sCD14) and procalcitonin." (PMID 33148245, 2020). "To further confirm that MAIT cell effector function is impaired during experimental sepsis, we evaluated IFNγ, TNFα, IL-17a, GM-CSF, and IL-10 protein expression in MAIT cells of lung tissue using flow cytometry." (PMID 33164745, 2020). "• Does the activity of IL-1RA, IL-4, IL-10, and/or TGF-β contribute to sepsis-associated immunosuppression?" (PMID 32676795, 2020). "M2 macrophages attenuate sepsis-induced AKI by upregulating IL-10 expression and suppressing TNF-α secretion." (PMID 32733471, 2020). "Sepsis-associated inflammatory cytokines, including IL-6, TNF-α, and IL-10, were significantly elevated in antibiotic-treated Rag2γc mice 12 days post infection compared to their levels in the B6 mice (p < 0.001)." (PMID 33488563, 2020). "Conversely, there was an increased production of anti-inflammatory cytokine IL-10 in the late phase of sepsis." (PMID 32089644, 2020). "We examined four relevant sepsis markers to assess host immune response phenotype: IL-10, TNFα, HLA-DR, and PD-L1." (PMID 32899240, 2020). "Both anti-TNF-α and recombinant murine IL-10 injected subcutaneously improved survival of E. coli sepsis in neonatal mice, indicating a role of IL-10 in improved outcome of sepsis in these animals." (PMID 33072121, 2020). "In this context, the aim of this exploratory study was to characterize IL-10 producing cells in sepsis through a novel whole blood intracellular staining approach by flow cytometry." (PMID 33613540, 2020). "In vivo EPC administration in sepsis increased plasma IL-10, suppressed lung vascular leakage, attenuated liver and kidney injury, and augmented miR-126 and -125b expression, which regulates endothelial cell function and/or inflammation." (PMID 32867826, 2020). "In a clinical study, the levels of IL-1β, IL-6, TNF-α, etc., except for IL-10, were inhibited in the late phase of sepsis, while, in an animal study, the immune suppression status was attenuated with administration of the adenovirus Ade-HIF-1α." (PMID 32089644, 2020). "On the other hand, bone marrow stromal cells administered to aged adult mice reduced sepsis-induced mortality and improved multiple organ function via reprogramming of host monocytes and macrophages that led to increased IL-10 production." (PMID 33072121, 2020). "There is enough evidence that IL-10 is one of the main cytokines involved in immune dysfunction in sepsis." (PMID 32230846, 2020).
Sepsis (continued). "In this study, we observed the severe inflammatory damage with increase of TNF-α, IL-6, and IL-10 in the ileum from the CLP-induced sepsis model, which was consistent with the previous study." (PMID 33376482, 2020). "During sepsis in mice, MDSCs accumulate in the late or chronic phase and both the pro-inflammatory cytokine IL-6 and the anti-inflammatory cytokine IL-10 play a critical role in the mediation of MDSC expansion." (PMID 32931721, 2020). "IL-33 release is involved in the polarisation of anti-inflammatory M2 macrophages that significantly release IL-10 that in turn aids in the expansion of Tregs and ultimately contributes to the immune suppressed phase of sepsis." (PMID 33336293, 2020). "By contrast, a continuous and gradual increase in the levels of IL-10 was observed in the wild-type mice especially after 6 days of the onset of sepsis, while a slight elevation in IL-10 was observed in S100A9 knock-out mice during the early septic phase only." (PMID 32931721, 2020). "The risk factors for VAE development include impaired immune response (lower human leukocyte antigen D-related expression, higher interleukin-10 expression) and sepsis progression with elevated SOFA score (especially in coagulation sub-score)." (PMID 32728165, 2020). "The overproduction of IL-10 was the main predictor of severity and fatal outcome of sepsis, and an increased ratio of IL-10/TNF-α was found in non-survived human patients." (PMID 33333934, 2020). "The levels of anti-inflammatory cytokines (IL-4 and IL-10) in plasma were found to be increased in the narciclasine treatment group compared to the untreated sepsis group." (PMID 32076015, 2020). "We demonstrated the feasibility of a novel technique for intracellular cytokine measurement in whole blood to monitor IL-10 production by circulating leukocytes in sepsis." (PMID 33613540, 2020). "XBJ stimulated Treg cell differentiation and inhibited Th17 cell differentiation in vitro, thus increasing the number of Treg cells that secreted IL-10 in sepsis rats and reducing neutrophil infiltration in the lung and kidney." (PMID 32082396, 2020). "IL-10 has been reported to be beneficial in various inflammatory diseases other than sepsis or systemic inflammation such as inflammatory bowel disorder, arthritis, sclerosis." (PMID 33158114, 2020). "In a cohort of 44 patients with severe sepsis and 15 healthy controls, IL-10 and IL-6 levels were substantially elevated in both serum and SBF in the septic patients." (PMID 33224151, 2020). "Conversely, the amount of IL-10 was lower in the adenovirus Ade-HIF-1α group compared with the sepsis model group and the Ade-control group." (PMID 32089644, 2020). "NVs induced IL-10 production in OMV-activated macrophages, which is consistent with the previous study showing that macrophage-derived IL-10 is necessary for the protective effect of MSCs in sepsis." (PMID 31370884, 2019). "Many reports have demonstrated that IL-10 is a major host defense mediator against sepsis-induced impairment." (PMID 30867482, 2019). "This was due to increased levels of MIP-1α and IL-10 in the plasma of young female animals 1 day after sepsis compared to the other groups." (PMID 31278440, 2019). "Here, we found that Siglec-G deficiency orchestrated the pro-inflammatory cytokines and anti-inflammatory cytokine IL-10, which protected mice from LPS-induced sepsis." (PMID 31781099, 2019). "IL-6 alone or in combination with other inflammatory markers such as procalcitonin, C-reactive protein, and IL-10 has been shown to identify patients with sepsis in both children and neonates." (PMID 31681719, 2019). "Serum cytokines, including IL6, IFNγ, IL1β, IL10, and TNFα were high suggesting the onset of sepsis in most of these mice even though there was a high degree of variation of bacterial load." (PMID 31121001, 2019).
Sepsis (continued). "Plasma levels of the proinflammatory cytokine IL-1β and the anti-inflammatory cytokine IL-10 were also elevated in mice with CLP-induced sepsis compared to sham-operated mice (p < 0.001 and p < 0.01 for IL-1β and IL-10, respectively)." (PMID 31792313, 2019). "More importantly, the innate immune responses in Rag2 KO rats, such as high serum levels of TNFa, IL-1, IL-6, and IL-10, and the development of thrombocytopenia also represent those seen in patients with sepsis." (PMID 31921873, 2019). "Most importantly, we identified a significant relationship between DNA methylation data and IL-10 and IL-6 cytokine levels, which are significantly increased in patients with sepsis, as well as with organ dysfunction." (PMID 31665078, 2019). "In murine sepsis, IL-10 has been reported to suppress the expression of IL-27 by activated F4/80+CD11b+ macrophages in an STAT3-dependent pathway." (PMID 31214168, 2019). "Selective knockout of β2-AR in innate immune cells in mice promotes death from sepsis in response to administration of an otherwise sub-lethal LPS dose, while co-administration of IL-10 rescues the mice." (PMID 31447835, 2019). "Animal models have suggested that the use of IL-10 or TGF-β blocking antibodies can improve survival in polymicrobial sepsis." (PMID 31014397, 2019). "Clinical studies in adults have reported increased IL-10 plasma levels in patients suffering from sepsis that are correlated with an increase in plasma levels of pro-inflammatory cytokines." (PMID 30873161, 2019). "We demonstrated that CMV is reactivated in sepsis as well as these patients presented a higher risk of developing septic shock and higher mortality rates, especially along the first weeks after reactivation, and our data suggest that IL-10 and NO may be involved in this process." (PMID 31227794, 2019). "Higher pro-inflammatory IL-6 and anti-inflammatory IL-10 levels have been associated with DIC and development of MODS in sepsis." (PMID 31681719, 2019). "LPS-injected Rag2 KO rats developed sepsis as indicated by increased TNFa, IL-6, IL-1b, and IL-10 levels and thrombocytopenia." (PMID 31921873, 2019). "Sepsis induced a generalized up-regulation of both human and murine plasma cytokines (TNFα, IL-6, IL-10, IL-8/KC, MCP-1); it was additionally aggravated in P-DIE vs. P-SUR." (PMID 31297113, 2019). "At 72 HPI, sepsis appeared to have progressed, with an increase in serum IFNγ, IL1β, IL10, and TNFα." (PMID 31121001, 2019). "On the other hand, late IL-7 treatment prolongs the sepsis induced expansion of immunosuppressive IL-10 producing B-lymphocytes and MDSC after sepsis." (PMID 30730978, 2019). "In fact, serum IL-10 concentrations were demonstrated in a human clinical study to correlate well with the sepsis severity and mortality, as also did the high IL-10/TNF-α ratio." (PMID 31075981, 2019). "As expected, sepsis induced an acute increase in both inflammatory (TNFα, IL1β, IL-6) and anti-inflammatory (IL-10) plasma cytokine concentrations." (PMID 31248453, 2019). "These propolypeptides are released into the blood when inflammatory mediators activate endothelial cells, and they are known to positively correlate with the amounts of IL-6, IL-8, and IL-10 in sepsis patients." (PMID 31568522, 2019). "The number of cells expressing IL-10 was greater (more than 10-fold, p < 0.0005, one of the greatest changes found in our study regarding cytokines) in leptospirosis and sepsis groups as compared to control in both red and white pulps." (PMID 31114579, 2019). "TNF-α is a vital proinflammatory cytokine, and IL-10 is a vital anti-inflammatory factor; both cytokines are involved in the development of sepsis." (PMID 31354717, 2019). "Similar to the findings at 48 hpi, the majority of both WT and Myd88−/− mice had very high levels of IL-6, TNF-α, and IL-10, indicative of progressing sepsis." (PMID 30642901, 2019).